INS (insulin)
Diseases named in the same sentence as INS in open-access papers (continued):
Sharing a sentence is not in itself a finding about the gene and the disease.
Hyperglycemia (continued). "Due to the hyperglycemic phenotype of T2D, protein stimulated endogenous insulin secretion may be seen as an acutely beneficial way to minimize postprandial hyperglycemia in those with prediabetes or T2D." (PMID 41602572, 2026). "One proposed mechanism of endocrine disruption suggests that the synergistic interaction with pituitary gonadotropins elicits androgen production in ovarian theca cells, thereby further impairing insulin sensitivity and leading to hyperglycemia, thereby contributing to an increased incidence of GDM." (PMID 41584407, 2026). "During 6 separate study days, GLP-2 (6 pmol/kg/min for 10 minutes and 2 pmol/kg/min for the following 90 minutes) and placebo (saline), respectively, were infused intravenously during insulin-induced hypoglycemia (∼2.5 mmol/L), euglycemia (∼5 mmol/L), or hyperglycemia (∼10 mmol/L)." (PMID 41541287, 2026). "We explore the impact of normalizing hyperglycemia through insulin therapy on urinary KIM-1 levels." (PMID 41601953, 2026). "However, despite identical type of pancreatectomy in both groups, hyperglycemia improved more significantly and insulin secretory function declined less after pancreatectomy in patients with PDAC." (PMID 41593307, 2026). "While preclinical studies suggest that chronic hyperglycaemia impairs spatial memory and that insulin may mitigate this effect in murine models, human data show mixed results." (PMID 41247493, 2026). "A sudden decrease in insulin secretion results in hyperglycemia and diabetic ketoacidosis, whereas nocturnal and early-morning hypoglycemia may be an initial symptom of hypoadrenocorticism." (PMID 41536580, 2026). "Indeed, it is known that stress can increase glucose levels (hyperglycaemia) and insulin requirements, at the same time promoting insulin resistance." (PMID 41486865, 2026). "Increasing protein content of foods is effective in reducing postprandial hyperglycaemia, but animal protein may exacerbate insulin sensitivity." (PMID 41615946, 2026). "Further heightening hyperglycemia, dysregulation of the pancreatic β-cell signaling pathway by leptin may impair insulin production in T2DM." (PMID 40722840, 2025). "Conversely, reducing hyperglycemia is known to improve insulin sensitivity." (PMID 40806520, 2025). "A deficiency of insulin or a lack of sensitivity of peripheral receptors to insulin lead to hyperglycemia." (PMID 40937273, 2025). "This protocol induces an obese, hyperglycemic, insulin-resistant phenotype that models key features of human T2D; in contrast, the same STZ dose does not cause hyperglycemia in insulin-sensitive, chow-fed controls." (PMID 41002949, 2025). "Patients with T1D require constant administration of insulin, which only alleviates the symptoms (hyperglycemia) but does not solve the root cause of the disease, namely, insufficient production of insulin." (PMID 41158127, 2025). "Persistent hyperglycemia despite insulin therapy prompted further evaluation." (PMID 40777711, 2025). "It is a noncommunicable disease, where the patient suffers from hyperglycaemia either due to deficiency of insulin or inefficient action of insulin, which can lead to complications if left untreated or poorly treated." (PMID 40771585, 2025). "It should be noted that CGMS offer information on nocturnal glycemic values and could facilitate the timely initiation of insulin therapy for GDM, thereby avoiding pregnancy complications caused by exposure to hyperglycemia in utero." (PMID 41303175, 2025). "We found that the incidence of hyperglycemia and whole-body fat mass was reduced, while there was no protection against cort-driven lean mass loss or insulin resistance." (PMID 40362449, 2025). "We also evaluated whether PBR could attenuate postprandial hyperglycemia by enhancing insulin secretion or peripheral glucose disposal, compared with WR." (PMID 40509433, 2025).
Hyperglycemia (continued). "Furthermore, elevated cortisol levels under HS are known to contribute to sustained hyperglycemia and impaired insulin signaling." (PMID 41012727, 2025). "Similarly, anthocyanins from black bean seeds can activate AMPK and GLUT4-related pathways, ameliorate hyperglycemia, and restore insulin sensitivity in murine models." (PMID 41471379, 2025). "Although anthocyanins may aid in hyperglycemia control by regulating glucose homeostasis, uricemia, glucose transport, insulin secretion, and gut microbiota, comprehensive research on their effects, mechanisms, and microbial metabolites is necessary." (PMID 39136514, 2025). "Emerging evidence highlights the important effects of fat and protein in postprandial hyperglycemia, suggesting that an increase in daily fat and protein intake, combined with appropriate insulin dose adjustments, might lead to better glycemic control." (PMID 41462804, 2025). "Flaxseed also elevates insulin sensitivity and regulates blood glucose concentrations, with lignans playing a role in improving insulin sensitivity by influencing glucose homeostasis and alleviating hyperglycemia‐induced cellular stress." (PMID 40918179, 2025). "However, the proportion of insulin-immunoreactive nitrergic neurons remained unchanged in all segments in chronic hyperglycemia." (PMID 40497986, 2025). "Preclinical studies in mouse models indicate that PI3Kα inhibition reduces glucose uptake in insulin-responsive tissues such as adipose tissue and muscle, resulting in hyperglycemia and compensatory insulin release from the pancreas, which diminishes the effect of PI3K inhibition." (PMID 40080721, 2025). "In addition, insulin and hyperglycemia stimulate IGF1 production, and the binding of IGF1 to its receptor activates the downstream signaling pathways that involve PI3K/AKT/mTOR and the RAS/RAF/mitogen-activated protein kinase (MAPK) pathways." (PMID 40430851, 2025). "The complex interplay between insulin resistance, beta-pancreatic cells’ secretory defects, growth hormone, cortisol, cytokines, and catecholamines may affect the development of stress hyperglycemia." (PMID 39860413, 2025). "These compounds exert a variety of metabolic effects: they modulate carbohydrate and lipid metabolism, reduce hyperglycemia and dyslipidemia, improve insulin sensitivity, support pancreatic β-cell function and adipose tissue regulation, and promote insulin secretion." (PMID 40722893, 2025). "Because the iNCDSS could provide dynamic and timely basal-bolus insulin adjustments, it may be applicable for managing hyperglycemia in acutely ill patients with pronounced glucose fluctuations, although further validation is needed." (PMID 40332936, 2025). "The elevated insulin secretion after gallic acid treatment positively reversed the impaired carbohydrate metabolism by lowering gluconeogenesis and enhancing glycolysis, ultimately leading to a reduction in hyperglycemia." (PMID 39861406, 2025). "From a clinical standpoint, suspicion should arise in patients presenting with erratic glycemic control, recurrent hypoglycemia, or alternating episodes of hyperglycemia and hypoglycemia, which are conditions driven by poor coordination between insulin action and carbohydrate absorption." (PMID 40161170, 2025). "The reduction in insulin and other metabolic parameters suggests that fg-SRLs primarily influence insulin secretion, which may contribute to postprandial hyperglycemia." (PMID 40142714, 2025). "In addition to impairing mitochondrial bioenergetics, hypoxia and hyperglycemia synergistically activate endoplasmic reticulum stress pathways, thereby disrupting insulin biosynthesis and triggering apoptotic signaling cascades." (PMID 40534855, 2025). "The pathway of hypomagnesemia leading to hyperglycemia may be due to both insulin action and insulin secretion." (PMID 39911868, 2025).
Hyperglycemia (continued). "Likewise, oxidative stress, caused by elevated reactive oxygen species (ROS) generation, affects pancreatic beta cells, limiting insulin release and exacerbating hyperglycemia." (PMID 40142617, 2025). "Taken together, these findings suggest that PG production under unstimulated conditions is minimal, and that the effect of cPLA2-KD may become apparent under stimulated conditions such as fever, hyperglycemia after a meal, and insulin-induced hypoglycemia." (PMID 40806659, 2025). "Additionally, insulin promotes glucose uptake in muscle and adipose tissues, thereby reducing blood glucose levels and ameliorating hyperglycemia." (PMID 40448078, 2025). "Hyperglycaemia was treated with continuous intravenous insulin." (PMID 40310300, 2025). "Moreover, these cells significantly alleviate hyperglycemia in diabetic mice after transplantation and produce human insulin into the circulation in a glucose-regulated pattern." (PMID 40913218, 2025). "PD pathophysiology is often ascribed to the decline in glucose metabolism regulation, the decreased sensitivity of insulin in insulin-dependent tissues, and the subsequent dysfunction of pancreatic β-cells, resulting in hyperglycemia and the overall dysregulation of insulin." (PMID 40650008, 2025). "Concurrently, the suppression of insulin secretion is offset by hyperglycemia and a decrease in insulin clearance, while during the recovery phase, catecholamine levels decline, leading to a restoration of insulin responsiveness and promoting blood glucose normalization." (PMID 41355999, 2025). "The flavonoids exert their antidiabetic effects by regulating carbohydrate digestion, insulin signaling and secretion, glucose uptake and improving cell proliferation, promoting insulin secretion, reducing apoptosis, and reducing hyperglycemia by regulating glucose metabolism in the liver." (PMID 40649331, 2025). "Mechanistically, exercise increases muscle glucose uptake and insulin sensitivity ‒ limiting chronic hyperglycemia and the formation of damaging advanced glycation end‐products ‒ while also stimulating the release of myokines (e.g., irisin, IL‐6) that exert anti‐inflammatory and anabolic effects." (PMID 40915183, 2025). "Hypoketonaemia, therefore, provides a sensitive indicator of hidden metabolic imbalance, signifying insulin-mediated suppression of hepatic ketogenesis that may coexist with euglycaemia or overt hyperglycaemia." (PMID 41586225, 2025). "Interestingly, 52% of respondents indicated initiating treatment with basal insulin for early hyperglycaemia once afternoon glucose levels surpass 140 mg/dl (7.8 mmol/l)." (PMID 39839808, 2025). "This initially may lead to significant postprandial hyperglycemia due to low insulin bioavailability." (PMID 40648766, 2025). "IR refers to diminished responsiveness of peripheral tissues (e.g., skeletal muscle, adipose tissue, liver) to insulin signaling, glucose uptake into these cells becomes inefficient, resulting in its accumulation in the bloodstream and consequent hyperglycemia." (PMID 40831951, 2025). "Our findings from DEGs and heat map revealed the intervention of EUG could enhance the functionality of islet β cells, augment insulin secretion, and mitigate hyperglycemia in T1DM mice." (PMID 39792010, 2025). "The mechanism of lorlatinib-induced hyperglycemia is unclear but may involve reduced insulin secretion." (PMID 41322009, 2025). "For example, low levels of SCFAs and high levels of BCAAs and LPSs may impair insulin signaling, leading to β-cell dysfunction, reduced glucose responsiveness, and insufficient insulin secretion, thus resulting in hyperglycemia." (PMID 40871631, 2025). "Possibly, the found association between admission glucose and IL-10 could be explained as a counter-regulatory response to insulin resistance and stress hyperglycemia due to acute illness." (PMID 39962379, 2025).
Hyperglycemia (continued). "Moreover, GCK-hyperglycemia patients received numerically higher total daily dose of insulin in every trimester compared to HNF1A-MD patients, but the differences were not statistically significant." (PMID 41409604, 2025). "By corroborating short-term trends with GA and capturing diurnal variations with CGM, veterinarians could develop more refined insulin dosing regimens and better detect asymptomatic hypoglycemia or hyperglycemia in diabetic dogs." (PMID 40723467, 2025). "In obese and lean mice treated with streptozotocin (STZ), there was a marked increase in serum sialic acid following insulin depletion, while hyperglycemia alone did not cause a similar elevation." (PMID 41301440, 2025). "These digital systems would need both the PWDI and healthcare staff to see inclusion of data items such as glucose levels, insulin doses administered, diet and any treatments taken for hypo or hyperglycaemia across the care pathway to allow proactive intervention." (PMID 40696540, 2025). "For example, the MIDD and IDPD subtypes, both characterized by modest HbA1c levels, were associated with elevated mortality, highlighting the prognostic relevance of insulin-deficient phenotypes independent of hyperglycemia." (PMID 40678231, 2025). "Alzheimer’s disease (AD) has a strong connection with hyperglycemia and insulin dysregulation." (PMID 40224020, 2025). "Oxidative stress induced by hyperglycemia may amplify insulin’s steroidogenic effect and promote theca-cell proliferation." (PMID 41384021, 2025). "Such an increase in the insulin response might contribute to a reduction in postprandial hyperglycemia, resulting in an improvement in MAGE." (PMID 41376852, 2025). "In fact, this clinical case report rather supports a behavioral hypothesis, where the concurrent hyperglycemia and erratic insulin administration led to excessive glycogenesis and hepatomegaly." (PMID 40757798, 2025). "The rise in fasting and post‐prandial plasma glucose will further increase the rate of VLDL‐TG production, ensuring excess fatty acid availability in the pancreatic islet, which would impair the acute insulin secretion following meals, and eventually post‐prandial hyperglycaemia will supervene." (PMID 39898429, 2025). "Patients exposed to chronic hyperglycemia seem to have reduced insulin signaling inskeletal muscle." (PMID 40179269, 2025). "Thus, the net result is an impaired incretin effect, leading to inadequate postprandial insulin secretion, sustained hyperglycaemia, and progressive pancreatic β-cell dysfunction, hallmarks of T2DM development." (PMID 41542178, 2025). "If hyperglycemia persists, progression to a full basal-bolus regimen or premixed insulin schedule may then be warranted." (PMID 41299307, 2025). "However, due to errors in drawing blood leading to a mistaken diagnosis of hyperglycemia, insulin therapy was inappropriately administered and the patient developed hypoglycemia." (PMID 41393585, 2025). "The sustained cortisol suppression at 24 h postoperatively correlated with dexmedetomidine's known inhibition of hypothalamic corticotropin-releasing hormone secretion, while attenuated hyperglycemia likely reflects improved insulin sensitivity through reduced catecholamine surge." (PMID 41143178, 2025). "However, chronic hypercortisolism or flattened cortisol rhythms disrupt this balance, leading to hyperglycemia and insulin resistance." (PMID 40076739, 2025). "Consequently, glucose in the bloodstream cannot enter the cells, leading to a condition in which islet cells continue to produce insulin, resulting in hyperinsulinemia alongside hyperglycemia." (PMID 40182806, 2025). "This may confound hyponatraemia in severe hyperglycaemia or prompt inappropriate potassium replacement during insulin therapy." (PMID 41246596, 2025). "In the pancreas, it has been hypothesized that GABAergic regulation, together with insulin, plays a role in decreasing hyperglycemia." (PMID 39974187, 2025).
Hyperglycemia (continued). "One main reason for recommending the initiation of an insulin‐based anti‐DM regimen in newly diagnosed DM patients with severe hyperglycaemia (glucose > 300 mg/dL or hbA1c > 10%–12%) is the understanding that such patients have insulinopenia and a state of glucose toxicity." (PMID 40482054, 2025). "The persistence of these metabolic alterations into early adulthood is particularly noteworthy, suggesting that intrauterine exposure to hyperglycaemia may programme long-term changes in insulin sensitivity." (PMID 40603555, 2025). "The preprandial hyperglycemia correction dose was based on a table with three columns (insulin-sensitive, usual, and insulin-resistant), which could be adjusted to a more sensitive or resistant profile according to the researcher’s decision." (PMID 39939862, 2025). "Excessive WG in early pregnancy predominantly involves adipose tissue, which may impair insulin sensitivity, exacerbate hyperglycemia, and disrupt lipid and protein metabolism." (PMID 41334337, 2025). "Instead, the model maintains mild hyperglycemia through remaining endogenous insulin production." (PMID 41223853, 2025). "The exact mechanism by which sirolimus and other mTOR inhibitors contribute to hyperglycemia remains unclear, but it is generally thought that these drugs increase insulin resistance by disrupting cellular signaling pathways." (PMID 39941214, 2025). "Even though loads of persuasion on glucose management including self-monitoring, regular insulin injection and consulting with endocrinologist has been made during hospitalization, he re-visited our clinic with hyperglycemia (random venous glucose: 55.08mmol/L) in a week." (PMID 40115026, 2025). "It is speculated that inhibiting the ALK gene can lead to decreased insulin secretion, leading to hyperglycemia." (PMID 41322009, 2025). "An long-term imbalance in energy between intake and expenditure is a key characteristic of individuals with obesity, and then chronic exposure to hyperglycemia, dyslipidemia, glucotoxicity impairs β-cell function and viability, leading to progressive deterioration of insulin secretion capacity." (PMID 40416523, 2025). "Hyperglycemia may contribute to bladder carcinogenesis through impaired immune function, chronic inflammation, and activation of insulin and IGF-1 signaling pathways." (PMID 40647559, 2025). "Glucocorticoid‐induced hyperglycemia is mediated by enhancing hepatic gluconeogenesis, reducing insulin synthesis and increasing destruction of pancreatic beta cells, decreasing glycogen synthesis and glucose absorption into the skeletal muscles, and increasing proteolysis and lipolysis." (PMID 40931439, 2025). "In addition, higher glucose concentrations are a direct consequence of insulin's diminished ability to regulate blood sugar, leading to hyperglycemia." (PMID 40342979, 2025). "If the islets are similar in size and β cell mass to WT mice, then our 20-week findings may be due to chronic hyperglycemia resulting in β cell demise and reduced β cell mass that cannot deliver adequate insulin." (PMID 40294908, 2025). "This disparity could stem from diabetic patients' increased tolerance to hyperglycemia, as well as their routine insulin therapy, which may provide neuroprotective benefits through its anti-inflammatory properties, mitigating brain damage." (PMID 40510212, 2025). "In this state, metabolic dysfunction arises from disrupted insulin signaling pathways, often triggered by recurrent diet-induced hyperglycemia and hyperinsulinemia, metabolic intermediates, chronic stress, inflammatory cytokines, hormonal imbalances, and exposure to endocrine-disrupting chemicals." (PMID 40565766, 2025). "Clinical observations have shown that BZYQF could improve insulin sensitivity and reduce hyperglycemia in T2DM patients." (PMID 40006017, 2025).